FAM99A (family with sequence similarity 99 member A)
Synonyms: FLJ42833
Gene: Long non-coding RNA gene on chromosome 11 (1,665,369 to 1,668,955, forward strand). Ensembl gene ENSG00000205866.
Diseases named in the same sentence as FAM99A in open-access papers:
FAM99A is named in the same sentence as 6 diseases in open-access papers, as found by Europe PMC text mining. Sharing a sentence is not in itself a finding about the gene and the disease. The quoted sentences say what the papers report.
hepatocellular carcinoma (3 papers, 2021 to 2025). A malignant tumor that arises from hepatocytes. "Further, this study examined the effects of FAM99A and FAM99B on the metabolic pattern and rate of hepatocellular carcinoma cells using Seahorse assay." (PMID 40693878, 2025). "FAM99A and FAM99B suppress glycolysis, proliferation, invasion, and migration of hepatocellular carcinoma under hypoxic conditions, which may be related to the miR‐1291‐mediated ceRNA mechanism." (PMID 40693878, 2025).
liver cancer (2 papers, 2021 to 2022). An epithelial or non-epithelial malignant neoplasm that arises from the liver. "HDAC1 promotes liver cancer metastasis via the FAM99A-miR92a signaling pathway." (PMID 33750478, 2021).
osteosarcoma (1 paper, 2021). A usually aggressive malignant bone-forming mesenchymal neoplasm, predominantly affecting adolescents and young adults. "Herein, we screened 6 osteosarcoma-related genes by lncRNA microarray, MALAT1, HCG9, FAM99A, FAM87B, DLEU2, and C8orf49." (PMID 34456631, 2021). "Six genes presented statistically significant expressions (P < 0.05) in osteosarcoma tissues versus paracarcinoma tissues and were screened, which were MALAT1, HCG9, FAM99A, FAM87B, DLEU2, and C8orf49." (PMID 34456631, 2021). "FAM99A, FAM87B, and C8orf49 have not been reported in osteosarcoma studies and are rarely reported in other cancers." (PMID 34456631, 2021).
tumor (4 papers, 2021 to 2025). "Another study also revealed that the downregulation of FAM99A was significantly associated with incomplete tumor capsule, tumor differentiation, recurrence, and poor prognosis of HCC patients." (PMID 36289466, 2022). "In HCC xenograft mice models FAM99A overexpression dramatically inhibited tumor growth, decreased cell necrosis, and infiltration of tumor tissues." (PMID 40596757, 2025). "It is well known that hypoxia‐mediated glucose metabolic reprogramming is an important factor in tumor progression; therefore, we examined the effect of hypoxia on FAM99A and FAM99B expression in HCC cells (HEPG2, SK‐1 and HCCLM3)." (PMID 40693878, 2025). "A subcutaneous xenograft tumor model demonstrated that overexpression of FAM99A significantly inhibited the tumor growth of HCC cells in vivo." (PMID 36289466, 2022). "Tumor weight was reduced in the mice of the FAM99A overexpression group versus those in the control group." (PMID 34765550, 2021). "Finally, we established a xenograft model and confirmed that the overexpression of FAM99A inhibits HCC tumor growth, downregulates GLUT1, and blocks nuclear translocation of STAT3 in vivo." (PMID 34765550, 2021). "The biological function of FAM99A on HCC cell proliferation, migration, invasion, and tumor growth was evaluated in vitro and in vivo." (PMID 36289466, 2022). "The results of univariate Cox regression analysis found that tumor size, BCLC stage, Child-Pugh classification grade, microvascular invasion, Edmondson-Steiner grade, and FAM99A expression level correlated with the OS of HCC patients (P < 0.1)." (PMID 36289466, 2022). "HE staining suggested that upregulation of FAM99A decreased cell necrosis and infiltration of tumor tissues compared to the negative control group." (PMID 36289466, 2022).
cancer (3 papers, 2021 to 2025). A tumor composed of atypical neoplastic, often pleomorphic cells that invade other tissues. "Given the important roles of tissue-specific lncRNAs in cancer, more studies are needed to further explore FAM99A as a diagnostic biomarker or therapeutic target for HCC patients." (PMID 36289466, 2022). "Our findings suggested that FAM99A exerted a cancer-inhibiting effect in HCC progression." (PMID 36289466, 2022). "Our results suggest that FAM99A exerts cancer-inhibiting effects on HCC progression, and it may be a promising prognostic indicator for HCC patients." (PMID 36289466, 2022).
FAM99A also shares sentences with these, for which no sentence is quoted: preeclampsia (1 paper).